CD44 (CD44 molecule (IN blood group))
Diseases named in the same sentence as CD44 in open-access papers (continued):
Sharing a sentence is not in itself a finding about the gene and the disease.
tumor (continued). "One such ligand is hyaluronic acid (HA), and CD44-HA interaction is known to regulate cytoskeleton dynamics and tumor progression in some contexts." (PMID 41049281, 2025). "Insummary, AKPC-siYT treatment effectively targets CD44+ cells,leading to a reduction in tumor growth both in vitro and in vivo." (PMID 40176316, 2025). "Inorganic nanoparticles like AuNPs can be functionalized with ligands, such as hyaluronic acid, to specifically bind receptors overexpressed on tumor cells (e.g., CD44 in OSCC), enhancing cellular uptake and therapeutic efficacy." (PMID 40837711, 2025). "CD44 inhibitors have been developed to block the binding of CD44 to HA or its downstream signaling pathways and inhibit tumor growth, invasion, and metastasis." (PMID 41439111, 2025). "In a xenograft model established by subcutaneous inoculation of NCI-H157-S15 cells into BALB/c nude mice, these antibodies showed distinct tumor targeting and significant blockade of Siglec-15 interactions with CD44, MAG, sialyl-Tn, and LRR4C ligands." (PMID 40507880, 2025). "Detection by staining against CD44 and Lgr5 demonstrated that all the tumoroids contained tumor stem cells, indicating that tumor stem cells in tumoroids were not influenced by 3DREs in our study." (PMID 40611658, 2025). "SPP1 (secreted phosphoprotein 1), also known as osteopontin, interacts with CD44 to promote tumor growth, metastasis, and immune evasion." (PMID 39955556, 2025). "While most prior studies focus on tumor-cell-intrinsic CD44 expression, CD44 is also expressed in stromal, immune, and pericyte-like cells." (PMID 40805225, 2025). "Immunofluorescent analysis of the resultant tumor sections with CD44 and CD146 confirmed the increase of CD44High pericytes." (PMID 41001759, 2025). "Studies have shown that inhibition of CD44 alters BCSCs’ properties including tumor initiation, adhesion, metastasis, and treatment resistance." (PMID 40676293, 2025). "We found a significant downregulation of phosphorylated ERK1/2 and Akt in tumor samples, providing a mechanistic link to key pathways downstream of CD44." (PMID 40342488, 2025). "In contrast, our study demonstrates that PTN derived from CD44+ tumor cells facilitates the phenotype transition of CAFs." (PMID 40069574, 2025). "Several studies have identified CD44 and CD133 as independent prognostic indicators in HCC, associated with increased tumor invasiveness and decreased survival." (PMID 40791212, 2025). "We also demonstrate that prior bevacizumab treatment (VEGF-A antagonist) preferentially reduces alternatively activated-like TAMs, whilst enhancing CD44 expression, in bevacizumab-treated tumours." (PMID 40140675, 2025). "This system better mimicked native tumor characteristics and higher expression of cancer stem cell markers (CD44 and CD24) compared to 2D models." (PMID 41050078, 2025). "Three immunotherapy drugs (TEID) are wrapped in a shell of hyaluronic acid to identify the tumor site by CD44 on the surface of the tumor cell membrane." (PMID 40270890, 2025). "A second, frequently recovered interface is SPP1 (osteopontin)–CD44, which is enriched at perivascular niches and couples macrophage programs to mesenchymal tumor traits and treatment resistance." (PMID 41357191, 2025). "Prior studies have demonstrated that SPP1 interacts with CD44 to promote tumour cell proliferation and metastasis, while FN1, through integrin‐mediated adhesion signalling, enhances cell survival and invasion and drives metastatic progression." (PMID 40988131, 2025). "Conversely, the downregulation of NFS1, GCLC, TP63, CD44, and SRC suggests a potential attenuation of antioxidant defense systems, thereby predisposing tumor cells to lipid peroxidation-mediated cell death." (PMID 40868287, 2025).
tumor (continued). "In giant cell tumors of bone, serglycin–CD44 interactions activate focal adhesion kinase, driving tumor progression." (PMID 40363706, 2025). "Subsequent histological evaluations of human HNSCC specimens revealed a tendency for an increased presence of CD44+ cancer cells in tumor zones in close proximity to neural niches with high CAV2 expression." (PMID 41330921, 2025). "Given that CD44 expression supports the stemness of tumor cells and significantly enhances tumorigenesis, it can be considered a valuable prognostic and therapeutic marker for guiding future treatment strategies." (PMID 40881916, 2025). "CD44 expression has been correlated with aggressive tumor behavior and epithelial-mesenchymal transition (EMT) in HCC patients after surgical resection." (PMID 40791212, 2025). "A high CD44/CD24 ratio, particularly the CD44 high/CD24 low phenotype, is characteristically associated with a higher proportion of CSCs within a tumor." (PMID 40227834, 2025). "Its upregulation enhanced tumor growth, invasion, epithelial-mesenchymal transition, and stem-like characteristics by increasing key markers (CD44, EpCAM, SOX2, and Nanog)." (PMID 40290725, 2025). "Taken together, multiple studies in the literature suggest that CD44 is expressed on tumor cells, including cancer stem cells, and is a promising target for targeted therapy in oncology." (PMID 39851489, 2025). "Across two different spatial modalities, we observed that surrounding Cd44 expressing hepatocytes in aged liver there was a consistent decline in T cell expression of Ifng, important for anti-tumor immunity." (PMID 41509421, 2025). "Subsequently, HA was applied as a coating on the NSs to enhance their biocompatibility and target tumor cells that overexpress CD44+." (PMID 40657185, 2025). "The observed increase in CD44 after scratching is in line with its frequent overexpression in GBM, which is associated with enhanced tumor invasion, migration, and poor prognosis." (PMID 41446725, 2025). "In summary, we validated five highly expressed proteins as specific targets for different tumour mutational backgrounds: CLIC3, CRABP2, and GMDS for AKT1E17K/TRAF7 tumours, CD44 for KLF4K409Q/TRAF7 tumours and ANXA3 for NF2−/− tumours." (PMID 40562609, 2025). "It has been shown that the interactions between hyaluronic acid (HA) and CD44 have demonstrated pivotal functions in drug resistance, angiogenesis, metastasis, and tumor cell survival." (PMID 40251609, 2025). "We validated CD44 with higher expression in KLF4K409Q/TRAF7 tumours by PRM-MS only due to limited sample availability and it displayed high significant upregulation compared to other targets tested." (PMID 40562609, 2025). "Immunohistochemistry staining for CD44, TGF-β, and VEGFA1 was performed in lung tissues of tumor-bearing mice, which demonstrated decreased positivity of CD44, TGF-β1 and VEGFA1 compared with control tumors." (PMID 41320721, 2025). "This clustering, occurring after detachment from the primary tumor, is facilitated by the cancer stem cell marker CD44 through intercellular CD44-CD44 homophilic interactions." (PMID 40076927, 2025). "CD44-targeted nanoparticles, functionalized with HA or chondroitin sulfate (CS), facilitate efficient tumor targeting and cellular internalization." (PMID 40363706, 2025). "In all examined primary tumor tissue samples, flow cytometry analysis demonstrated clear expression of putative cancer stem cell markers CD44, CD133, and CD166." (PMID 41303421, 2025). "Active targeting represents a key advancement in nanoparticle-based drug delivery for OSCC, relying on the functionalization of nanoparticles with ligands that bind selectively to receptors overexpressed in tumor cells, such as CD44 and folate receptors." (PMID 40837711, 2025). "Given this increased abundance of CD44-expressing hepatocytes in livers of aged male mice and their known role in tumor initiation, we set out to better define these aged CD44-expressing hepatocytes." (PMID 41509421, 2025).
tumor (continued). "This tumour-suppressive effect was mediated through the clustering of the CD44 extracellular domain, a cell-surface glycoprotein known to interact with HA." (PMID 39852021, 2025). "SPP1 can engage receptors like CD44, activating NF-κB signaling and establishing a feed-forward loop that sustains macrophage polarization and promotes tumor progression." (PMID 41425545, 2025). "One of the studies reported that tumor-derived OPN activates Twist1-dependent gene expression by binding to CD44 and αvβ3 integrins on the CAF via Akt and ERK pathway, causing tumor cells to undergo EMT." (PMID 39858015, 2025). "Hyaluronic acid can bind to various receptors on the cell surface, including CD44, which is expressed at a high level on tumor cells." (PMID 39851489, 2025). "The only observed change was an increase in CD44+ splenocytes in calcitriol-treated young 4T1 tumor-bearing mice." (PMID 40894304, 2025). "This approach increased doxorubicin cytotoxicity sixfold in CD44+ cells within 3D tumor spheroids and significantly reduced tumor size in an orthotopic xenograft model, with minimal systemic toxicity." (PMID 40277711, 2025). "The Tumor-0 subcluster comprised the majority of cells, with upregulated genes typical of tumor markers, such as Ccnd1, Cd44, Krt7 and Plau." (PMID 41332581, 2025). "Distinct isoforms, including CD44s, CD44v, and soluble CD44, contribute to tumor initiation, invasion, therapy resistance, and immune dysregulation through interactions with HA, osteopontin, growth factor receptors, and proteases." (PMID 41009438, 2025). "Treatment with anti-OPN or anti-CD44 antibodies can reverse the inhibition of T cell activity by tumor cells, thus inhibiting tumor growth." (PMID 40093009, 2025). "For example, at the cut-off value of ≥5% of tumour cells with positive immunostaining, CD44 expression was detected in 95% of the cases examined, and 16% of the cases were CD109 positive." (PMID 40227788, 2025). "By regulating the alternative splicing of CD44 and affecting its variant balance, it can regulate the adhesion, migration, signaling, and EMT processes of tumor cells, which has a significant impact on the occurrence and development of tumors." (PMID 40046628, 2025). "A recent study demonstrated a novel tumor-suppressive mechanism of MEN1 through the regulation of the CD44 alternative splicing." (PMID 41369362, 2025). "Mechanistically, CDK4/6i enhances the accumulation and activation of M1 TAMs and promotes the M2 to M1 polarization via augmented interaction of the macrophage migration inhibitory factor (MIF)-CD44/CD74 axis between tumor cells and macrophages." (PMID 41082324, 2025). "Functional analyses suggested that tumor-associated macrophages (TAMs) secrete SPP1, which binds to CD44 on neoplastic-stemness cells, activating the PI3K/AKT pathway and driving lncRNA transcription to promote metastasis." (PMID 40076844, 2025). "We have demonstrated that a multifunctional molecule such as CD44 can not only promote migration and invasion of tumor cells but also participate in the development of tumor recurrence through hypoxia-regulated expression of CD44." (PMID 40002787, 2025). "CD44-positive CSCs located at tumor leading edge exhibit an EMT phenotype and possess the capability for distant metastasis." (PMID 40069574, 2025). "High CD44 expression in tumor cells significantly correlated with DFS (p = 0.007) and MFS (p = 0.011) but not with OS." (PMID 40647395, 2025). "We observed that Rha promoted the apoptosis of SCC9‐CisR cells and inhibited their tumor sphere‐forming ability, accompanied by reduced CD44 and SOX2 mRNA levels." (PMID 40608530, 2025). "Variability in the type, location, and intensity of these modifications contributes to the considerable functional heterogeneity of CD44, especially in the context of tumor pathologies and interactions with the extracellular matrix." (PMID 41009438, 2025).
tumor (continued). "For instance, OPN-R3 inhibits the binding of OPN to αvβ3 integrin and CD44, suppressing tumor progression and metastasis in breast cancer models." (PMID 41425545, 2025). "RHAMM interacts with ERK1/2 to regulate tumour metastasis and is necessary for CD44-mediated skin wound healing." (PMID 41301516, 2025). "Marangoni and colleagues showed that antibody-mediated CD44-targeting in human BC xenografts (HBCx) significantly reduces tumor growth, an effect attributed to the induction of growth-inhibiting factors." (PMID 40443562, 2025). "Serial tumor biopsies revealed a decrease in CD44+/CD24− cells, ALDH1+ cells, and mammosphere-forming efficiency." (PMID 40869256, 2025). "Our study explores the application of HER2-specific CAR NK cells against both trastuzumab-sensitive (CD44−) and trastuzumab-resistant (CD44+) HER2-positive tumor models, providing insight into the potential and limitations of these innovative therapies." (PMID 40075578, 2025). "They observed enriched SPP1+ TAMs in chemotherapy‐resistant patients, suggesting SPP1+ TAMs directly interact with CD44 on tumour cells to promote chemoresistance." (PMID 40954554, 2025). "In this study we explore the molecular mechanisms by which CD44 knockdown (kd) leads to such substantial changes of tumor properties." (PMID 40438109, 2025). "CD44 showed a more pronounced variation, suggesting its higher relevance in assessing tumor aggressiveness." (PMID 40005368, 2025). "The inhibition of CD44 activity by the administration of an anti-CD44 antibody also inhibited the development of local and metastatic tumor nodules by CD90+ cells." (PMID 40890130, 2025). "CD44 is a transmembrane glycoprotein involved in cell adhesion, migration, and signal transduction; it plays a critical role in tumor proliferation, metastasis, and resistance to apoptosis." (PMID 41303421, 2025). "Vaccination with CD44/EpCAM peptide-primed dendritic cells enhances anti-tumor immunity and induces apoptosis." (PMID 41438763, 2025). "HA is a major component of the extracellular matrix (ECM) that activates signaling pathways promoting tumor progression by interactions with its major cell surface receptor, CD44." (PMID 41303585, 2025). "Breast CSCs are typically characterized by a CD44+/CD24−/low phenotype, which is associated with increased tumor-initiating potential and self-renewal capacity." (PMID 40881916, 2025). "CD44 (a key CSC marker)-positive cells purified from HNSCC retain the tumor heterogeneity observed in the original tumor." (PMID 40136652, 2025). "To further investigate how CD44+ tumor cells remodel the TME, we analyzed the communications between these cells." (PMID 40069574, 2025). "In aged 67NR tumor-bearing mice, the only observed change was an increase in CD44+ cells in the spleen." (PMID 40894304, 2025). "UMAP plots of LGALS9 and CD44 expression in both tumor and immune cells were visualized, confirming the importance of this signaling axis." (PMID 40933995, 2025). "The results showed that CD44-/CD105- cells not only induced tumor growth in mice, but also that the tumors had a longer T1 time and a different metabolic pattern than other tumors." (PMID 40642092, 2025). "Conversely, tumors exhibiting a high EpCAM/CD44+ cellular profile maintained a differentiated phenotype, mirroring the morphological and phenotypic heterogeneity of the primary tumor mass." (PMID 40647400, 2025). "Benefiting from the involvement of hyaluronic acid, the prepared IC@PCH NPs not only targeted CD44 on the surface of tumor cells but also showed a longer in vivo circulation time." (PMID 40376201, 2025). "Consistently, TCF1OE tumours formed robust organoids ex vivo and co-expressed CD104/CD44 with E-cad/VIM as compared to control tumours." (PMID 40764669, 2025). "In mouse models, the use of anti-SPP1 or anti-CD44 antibodies, either alone or in combination with PD-1 antibodies, significantly reduced tumor burden." (PMID 40867844, 2025).
tumor (continued). "The growth factor- and cytokine-rich tumor microenvironment also significantly contributes to CD44 regulation." (PMID 40363706, 2025). "One promising aspect in the future of CD44-targeted nanocarriers is the development of delivery systems that can detect and adjust to changing circumstances inside the tumor microenvironment." (PMID 41367861, 2025). "Tumor cells followed a similar trend, increasing in CD74 MIF (β = 0.219, p = 0.005) and MIF CD44 (β = 0.190, p < 0.0001), further supporting their role as hubs of immune activation and tumor presence in advanced disease." (PMID 40364843, 2025). "CD44, a receptor for hyaluronan and osteopontin, promotes cell proliferation, cell cycle progression, and tumor-initiating cell maintenance, then tumor growth and therapy resistance." (PMID 40106404, 2025). "Low CD44 expression allows BCSCs to differentiate into normal cells, whereas its suppression impedes tumor formation." (PMID 40923026, 2025). "Both double and triple combinations decreased proliferative tumor cells (Ki67+, Vimentin+ and CD44+) and TAMs (F4/80+) compared to single agent treatments." (PMID 40568104, 2025). "It has been reported that subpopulations of CAFs expressing the CD44 marker can support self-renewal of melanoma CSCs through direct cell–cell contacts, which simultaneously increases the tumor’s resistance to therapies." (PMID 40806546, 2025). "HPV-positive tumor cells had increased IDO1, HLA-DR, and Ki67 positivity, whereas HPV-negative tumor cells were more frequently CD44 positive, reflecting a more stem-like phenotype." (PMID 41254766, 2025). "CD44 is a transmembrane protein, also interacting with MMPs, with a well-established role in tumor progression, invasion, and metastasis in OS." (PMID 41226578, 2025). "S27 (B and C), the suspended 4T1-SP cells formed characteristic tumor spheroids and exhibited a high proportion of CD44+/CD24− cells, confirming CSC enrichment." (PMID 40901943, 2025). "For instance, HA-based liposomes designed to target CD44-positive CSCs have been shown to enhance therapeutic efficacy and inhibit tumor growth." (PMID 40363706, 2025). "A substantial proportion of the tumor‐infiltrating memory T cells differentiated from central memory T cells (CD44+CD62L+CD69−) to effector memory T cells (CD44+CD62L−CD69−)." (PMID 39761175, 2025). "Once across the BBB, tumor specificity is achieved through ligands targeting overexpressed receptors such as EGFRvIII, IL13Rα2, and CD44." (PMID 40944840, 2025). "The downregulation of miR-126 significantly inhibited tumor growth in HBs and reduced the proportion of CD44+ CD90+ CD133+ cells, increasing the expression of IL-6, Oct4, SRY, TGF-β, and β-catenin in mouse tumor tissues." (PMID 41393242, 2025). "In vitro and in vivo fluorescence imaging confirmed tumor-specific accumulation in CD44-positive A549 tumor cells and lung tumor-bearing mice, via CD44-mediated endocytosis and subsequent cytosolic release." (PMID 41140492, 2025). "Hyaluronic acid receptors, including CD44, are widely present in the body and are found not only on tumor cells." (PMID 39851489, 2025). "Hematoxylin‐Eosin staining showed that the presence of CMTM4 in tumor tissue increased atypical cell production, and Immunofluorescence (IF) staining confirmed a significant reduction in Ki67‐ and CD44‐positive (invasive marker) regions in ID8/CMTM4 KO tumors." (PMID 40433989, 2025). "CD44, CD24, Prominent-1 (CD133), and EpCAM are selectively expressed or elevated in CSCs, and are directly associated with tumor recurrence." (PMID 40069421, 2025). "Our findings revealed a distinctive layered ring-like structure within CRC tissues, where CD44+ tumor cells exhibiting high stemness were positioned at the tumor’s leading edge." (PMID 40069574, 2025).